CD44 (CD44 molecule (IN blood group))
Diseases named in the same sentence as CD44 in open-access papers (continued):
Sharing a sentence is not in itself a finding about the gene and the disease.
breast carcinoma (continued). "Co‐occurrence of CD44 and CD133 was furthermore apparent in these peripheral populations, pointing toward the emergence of a CD44+ CD133+ breast cancer population at the periphery of the confined spheroids." (PMID 40569213, 2025). "In the context of tumorigenesis, CD44 is increasingly recognized as an essential marker and functional component in breast cancer stem cells, playing a vital role in their maintenance, tumorigenesis, and malignancy." (PMID 40430044, 2025). "The nanomicelle structure is expected to accumulate at tumour sites through EPR and be internalized by CD44-overexpressing breast cancer cells." (PMID 40264886, 2025). "It is well known that CD44 is a cell surface glycoprotein that serves as a specific receptor for hyaluronan and plays a crucial role in breast cancer cell adhesion, migration, and invasion." (PMID 39932626, 2025). "This electrochemical biosensor platform can serve as a valuable tool for diagnosing human cancer by recognizing CD44-overexpressing cell surfaces, such as those of breast cancer cells." (PMID 41440277, 2025). "This is based on the observation of the association between CD200 expression and other CSC markers, such as CD44+/CD24− in breast cancer, CD44+ in prostate cancer, CD133 in CRC, BMI1 and Shh in HNSCC." (PMID 41233805, 2025). "Our findings revealed that BAP31 expression was elevated in breast cancer cells, and its knockdown led to a decrease in both sphere formation and the CD44+CD24− population." (PMID 40332113, 2025). "CD44 is crucial for adhesion, migration, and invasion in breast cancer because it promotes cell proliferation, tumor progression, and angiogenesis." (PMID 39932626, 2025). "It was found that quercetin suppressed breast cancer stem cells (CD44+/CD24−) derived from the MCF7 cell line through the down-regulation of m-TOR, PI3K, and PI3K-AKT pathways and the decreased expression of Bcl-2 protein and cyclin D1." (PMID 39859345, 2025). "In conclusion, modification of LNPswith the CD44-specific AKPClipopeptide greatly enhanced the in vivo tumor targetabilityof LNPs to breast cancer cells that had metastasized to the tail andwere located in situ in the hindbrain." (PMID 40176316, 2025). "Clark and colleagues were among the first to identify that CD44+CD24−/low breast cancer CSCs were capable of initiating tumours, whereas CD44+CD24+ cells were virtually incapable of forming tumours." (PMID 40665579, 2025). "Breast cancer stem cells (BCSCs) exhibit distinct marker profiles defined by CD44, CD24, and ALDH expression." (PMID 41373619, 2025). "It has been demonstrated that HAS2 is required for the induction of the EMT program mediated by TGF‐β specifically in breast cancer cells coupled with the participation of hyaluronan receptor CD44." (PMID 40542654, 2025). "Capsaicin has an anti-tumor effect on breast cancer stem cells through the down-regulation of the Notch signaling pathway and decreased mammosphere formation of CD44+/CD 24− cancer cells." (PMID 39859345, 2025). "This research suggested that breast cancer cells can disseminate chemoresistance via exosomal proteins, particularly CD44." (PMID 41440277, 2025). "Targeting CD44-positive populations or their supporting signaling pathways represents a promising strategy to overcome therapy resistance in HER2-positive breast cancer." (PMID 40430044, 2025). "Silencing SDC1 in breast cancer cells inhibited their proliferation and reduced the protein levels of stem markers CD44, CD133, and SOX2." (PMID 41364407, 2025). "Flow cytometry analysis revealed a decrease in the breast cancer stem cell population (CD44+CD24‐) in MDA‐MB‐231 cells from 95.5% to 76.5%, while in BT‐549 cells, the percentage remained nearly constant (62.1%–61.2%)." (PMID 40059964, 2025). "It has been demonstrated that activated NK cells are capable of preferentially killing the CSC populations in breast cancer (CD24−/CD44+), pancreatic cancer (CD24+/CD44+), and glioblastoma (CD133+)." (PMID 41346579, 2025).
breast carcinoma (continued). "Previously reported putative CSCs markers for other solid tumors (CD44 in breast cancer and CD133 in brain tumor) were used to identify HN-/OSCC CSCs and then isolated and xenotransplanted in mice to observe for tumor formation." (PMID 39335624, 2024). "The combined treatment induces G2/M cell cycle arrest and disrupts the physical association of CD44 with NANOG and MDR1 in MDA-MB-231 cells, thus overcoming breast cancer resistance and promoting cancer cell death." (PMID 39519572, 2024). "A study of human breast cancer showed that CD74 interacted with CD44 to promote tumorigenesis and metastasis of MDA-MB-231 cell through the regulation of RHOA." (PMID 38874510, 2024). "CD24 and CD44 expression on breast cancer cells have been shown to correlate with disease aggressiveness and risk of metastasis." (PMID 40051976, 2024). "In breast cancer cells, a positive feedback loop coupling CD44 splice isoform and HAS2 results in increased PI3K/Akt activation which ultimately leads to cell death resistance." (PMID 37953485, 2024). "A study showed that CD44 splice isoform switching regulates the breast cancer stem cell state, with the standard isoform (CD44s) responsible for stemness and the variant isoform (CD44v) responsible for proliferation." (PMID 39145451, 2024). "Of the tumor-intrinsic gene response, we previously discovered that co-culture with MSCs upregulated LCN2, an iron sequestering protein, and CD44, a marker of stem-like cells, in breast cancer cells." (PMID 39480488, 2024). "CD24lo/CD44hi (expressing high levels of CD44 and low levels of CD24) is a major hallmark of breast cancer stem cells." (PMID 38285090, 2024). "Another study demonstrated that in breast cancer cell lines, HA/CD44/RHAMM forms a signaling complex with ERK‐1,2 to sustain tumor invasiveness." (PMID 37953485, 2024). "In vitro, spheroid formation assay validated the cytotoxic effects of CA9-BPS-Cu(II) to CD133+ and CD44+/CD24− MDA-MB-231 breast cancer cells." (PMID 38609981, 2024). "In this context, it was investigated how CD24−/CD44+ breast cancer stem cells would respond to relevant drug applications in 3D culture conditions rather than monolayer culture." (PMID 38910198, 2024). "One such receptor is CD44, which has been shown to be highly overexpressed in many breast cancers and other types of cancer cells." (PMID 38931956, 2024). "We evaluated changes in CD-44 expression in two mammary carcinoma cell lines (MCF10A and MDA-MB-231) after exposure to X-ray (2 or 10 Gy)." (PMID 38172135, 2024). "Here, it was examined and compared the potential of the HA-Cd-NC to deliver Cro into different breast cancer cell lines with different amounts of CD44 on the surface and cell death induction in these cells." (PMID 38966182, 2024). "We have previously observed that stem-like ALDHhiCD44+ breast cancer cells have a propensity to metastasize to the lung in vivo, and that the interaction between lung-derived soluble factors and CD44+ breast cancer cells supports metastatic behaviour." (PMID 38581619, 2024). "Breast cancer spheroids enriched with CD44+/CD24- cells grew tumors and targeting these CSCs with niclosamide inhibited spheroid formation, induced apoptosis, and inhibited tumor growth in mice." (PMID 38737455, 2024). "In this study, we found that TSP50 significantly increased the CD44+/CD24− subpopulation of breast cancer cells." (PMID 39030572, 2024). "The expression of IMP3 in CD44+CD24‐ESA+ cell clusters in breast cancer tissue was significantly upregulated." (PMID 38358034, 2024). "In breast cancer and bladder cancer, CD44 knockdown inhibits cell invasion and tumorigenicity by blocking STAT3 phosphorylation." (PMID 38385088, 2024). "As a CSC marker, CD44 has been reported in breast cancer, colorectal cancer, pancreatic cancer, and head and neck squamous cell carcinoma." (PMID 39518076, 2024).
breast carcinoma (continued). "The presence of undifferentiated CD44+CD24−/low tumor cells is an unfavorable prognostic marker in patients with breast cancer, and the increased proportion of CD44+CD24−/low cells is an indicator of probable metastases in the lymph nodes." (PMID 38534924, 2024). "According to published research, patients with high levels of VEGF and CD44 expression in breast cancer have a comparatively short survival period." (PMID 38919615, 2024). "After that, Cro was loaded on HA-Cd-NC and it was used for the treatment of a panel of human breast cancer cell lines with varying degrees of CD44." (PMID 38966182, 2024). "A substantial positive correlation was observed between HSF1 and either ALDH1A1 (p = 0.0009) or CD44 (p < 0.0001) in breast cancer patients with high HER2 expression." (PMID 38646654, 2024). "For instance, CD44-facilitated ERBB2/3 heterodimer formation serves as a mechanism that has been reported to mediate metastasis in breast cancer models." (PMID 39518076, 2024). "Our recent study utilized an established expression score scale for HER2 in breast cancer to assess CD44 expression." (PMID 38672650, 2024). "In breast cancer, CD44 plays key roles in aggressive tumor behavior, tumor progression, CSCs trait induction, and prognosis." (PMID 38783892, 2024). "Based on the study, membrane derived soluble CD44 secreted by breast cancer cells triggered IL1-β expression in TAMs promoting cancer cell EMT and metastasis." (PMID 39044824, 2024). "It was also proved that circHIF1A was transferred to breast cancer cells by hypoxia CAFs exosomes and promoted sponging miR-580-5p through the expression of CD44, enhancing the formation of breast cancer cell stemness and tumorigenesis." (PMID 38302430, 2024). "To investigate the relationships between LOXL2, PEAR1, and PEAR1 Ser891 phosphorylation and CD44 in breast cancer, we subjected human TNBC samples to IHC." (PMID 39145451, 2024). "Scientists have developed HA-modified magnetic nanoclusters to detect CD44-overexpressing breast cancers using MRI." (PMID 39771471, 2024). "Hinokitiol treatment significantly reduced CD44 protein expression levels in all three breast cancer cell lines, indicating its potential to inhibit stemness properties and limit the capacity for self-renewal in breast cancer cells." (PMID 38612715, 2024). "The HA-DOX- cisplatin micelles demonstrated significant improvement in drug release under acidic conditions, leading to higher cellular uptake and more effective inhibition of CD44 positive breast cancer cells." (PMID 38799466, 2024). "In agreement with our findings, tGLI1 and GP130 co-overexpression significantly increased the CD44+/CD24− breast cancer cell population in both SKBR3 and BT20 cells." (PMID 39768178, 2024). "The METABRIC data cohort identified a significant correlation between overexpression of CD44/ALDH1A1 and HSP90 or HSF1 in patients with HER2-positive breast cancer, which was associated with relatively poorer overall survival." (PMID 38646654, 2024). "In this study, we investigated the role of CD44-positive extracellular vesicles secreted by highly metastatic breast cancer cells (for, e.g., mouse mammary carcinoma cells using Luc2) in pre-metastatic niche formation." (PMID 39273689, 2024). "Then, the Cd-NC was targeted toward breast cancer cells by adding HA, a ligand for the CD44 cell surface receptor." (PMID 38966182, 2024). "CD44 has been widely studied as a marker for stem cells with links to promoting metastasis in breast cancer." (PMID 39199676, 2024). "Of note, a pro‐metastatic and pro‐mesenchymal role of CD44 isoform 4 was previously shown in other cancer types, including breast cancer, hepatocellular carcinoma and squamous cell carcinoma." (PMID 37849446, 2024). "CSCs are also called TICs, because when inoculated into severe combined immunodeficiency disease (SCID) mice, represent the minority of breast cancer cells capable of forming new tumours and are CD44+/CD24–/low/lineage–4." (PMID 39003349, 2024).
breast carcinoma (continued). "We previously demonstrated that CD44+CD24− cancer cells are enriched in basal-like tumors compared with other breast cancer subtypes and that CD44+CD24− cancer cells have heightened IL-6/JAK2/STAT3 signaling activity compared with other tumor cells." (PMID 38297352, 2024). "Kamalesh Dattaram Mumbrekar describes the sensitivity of mutations in the CD44 and MAT1A genes to acute skin reactions in breast cancer patients undergoing radiotherapy." (PMID 38380359, 2024). "According to TCGA data for breast cancer, TSP50 mRNA expression was positively correlated with OCT4, ALDH1, NANOG and CD44 markers associated with BCSC." (PMID 39030572, 2024). "There were minimal quantity CD44+CD24- stem CTCs expressing integrin β4+ in peripheral blood of breast cancer patients." (PMID 38250718, 2024). "In summary, highly metastatic mouse mammary carcinoma cells express the hyaluronan receptor CD44 and secrete CD44-positive EVs." (PMID 39273689, 2024). "The first evidence for the presence of CSCs in solid cancers emerged from identifying CD44+/CD24-/low lineage cells in immunocompromised mice with transplanted human breast cancer cells." (PMID 38737455, 2024). "In breast cancer, populations with CD44+CD24-/low surface markers and high ALDH1 activity are enriched for cells with stem cell properties." (PMID 38886396, 2024). "The expression profile of CD44+/CD24− proteins is widely accepted as a molecular marker of breast cancer stem-like cells." (PMID 38392969, 2024). "Breast cancer cells that overexpress MEG8 also showed a lower proportion of CD44 + CD24- cells, which are considered tumor-initiating cells in breast tumors, except from MDA-MB-468." (PMID 39706842, 2024). "In human breast cancer cells, CD44 knockdown suppressed both the mRNA and protein expressing of c‐Src and its downstream MAPK signal." (PMID 38783892, 2024). "In breast cancer, this pathway is pivotal for the development of human CD44+CD24- stem cell-like cancer cells, and the inhibition of JAK2 prevents xenograft growth." (PMID 39079960, 2024). "The CD44+CD24− cell population has been shown to identify a subpopulation of cells in breast cancer enriched for BCSCs." (PMID 39469631, 2024). "Studies have shown that the JAK2-STAT3 signaling pathway was involved in the growth of CD44+/CD24− stem-like cell populations in human breast cancer cells." (PMID 38872110, 2024). "Several studies have previously investigated the interaction between SRGN and CD44, mostly in cancers, such as breast cancer and non-small cell lung cancer." (PMID 38287411, 2024). "We investigated the role of CD44-positive EVs secreted by highly metastatic mouse mammary carcinoma cells in forming a premetastatic niche." (PMID 39273689, 2024). "Since the CI values calculated in all cell groups used in the study (MCF-7, CD24−CSCs and CD44+CSCs) were below 1 (Fa = 0.5), it was clearly demonstrated that 5-Fu and Dox had a synergistic effect on breast cancer." (PMID 38910198, 2024). "With this coating and using the classical EDC/sulfo-NHS cross-linking procedure, we also demonstrate the successful multiplexed immunolabelling of Her2, CD44, and EpCAM in breast cancer cell lines (SK-BR-3 and MDA-MB-231)." (PMID 39170968, 2024). "This platform was designed for the detection and evaluation of CD44 expression on breast cancer cells, where ZnCQDs were combined with gold nanoparticles and magnetic beads to boost the ECL signal." (PMID 38730959, 2024). "CSCs have specific markers on their surface, along with general antigens and receptors, which are organ‐specific, for example, CD44+/CD24 in breast cancer, CD133 in brain tumors, and epithelial‐specific antigens in pancreatic cancer." (PMID 39217459, 2024). "In breast cancer xenograft models, depletion of HA or loss of CD44 were both shown to reduce CCL2 production in vitro and loss of CD44 impaired macrophage recruitment and tumour induction in vivo." (PMID 38791926, 2024).
breast carcinoma (continued). "MCF-7-derived breast cancer stem cells (CD24−/CD44+) were inoculated at a concentration of 5 × 105 cells/60 μL per gel in three replicates, and cell matrices were incubated at 37°C and 5% CO2." (PMID 38910198, 2024). "In colon and breast carcinoma cells, elevated levels of HA result in the formation of a signaling complex involving CD44 and ErbB2, along with PI3K, ezrin, HSP90, and CDC37." (PMID 37953485, 2024). "In clinical studies whit human breast cancer tissue obtained before and after chemotherapy found that CD44 + /CD24- or ALDH1 + tumor cells significantly increased after chemotherapy." (PMID 39180549, 2024). "As a therapeutic target, CD44 has held some promise in the past, e.g., anti-CD44 mAb therapy in breast cancer xenografts, reducing tumor growth and relapse post-chemotherapy." (PMID 38983848, 2024). "This study aims to elucidate the role of CD44-positive extracellular vesicles secreted by highly metastatic mouse mammary carcinoma cells (Luc2 cells) containing VEGF-A and VEGF-C in pre-metastatic niche formation." (PMID 39273689, 2024). "Another study showed that breast cancer cells with high ALDH activity or high CD44 with low CD24 expressed high levels of type I tyrosine kinase like orphan receptor ROR1 and had greater capacity to form spheroids." (PMID 38737455, 2024). "PDPP, a polyvalent-directed peptide polymer, recognized breast cancer stem cells using combinational peptides P6 and P7, displaying a higher affinity and inhibition potential against the CD44 biomarker in breast CSCs." (PMID 38672650, 2024). "In breast cancer, CD44+ CSCs are shown to exhibit high tumorigenicity and the ability to establish tumor heterogeneity following transplantation into mice." (PMID 39605477, 2024). "In HER2-positive breast cancer, CSCs are characterized by the CD44 high/CD24 low phenotype and ALDH1 expression." (PMID 38920716, 2024). "Meanwhile, TSP50 shRNA-stably transfected breast cancer cells revealed a lower CD44+/CD24− cell ratio and ALDH activity." (PMID 39030572, 2024). "Breast cancer patient-derived CD44+ CSCs cannot be maintained in culture and were therefore propagated in NOD-scid gamma (NSG) immunocompromised mice as human patient-derived xenografts (PDXs)." (PMID 39605477, 2024). "Immunohistochemical analysis of the tumor tissue sections with antibodies (Table ST3) revealed a significant increase in the colocalization of GFP and CD44 in the CD24−/CD44+‐breast CSC as compared with the CD24+‐breast cancer cell xenotransplanted groups." (PMID 38522013, 2024). "This experiment supported our results by showing that CD44-positive EVs secreted by breast cancer cells are essential for intercellular communication." (PMID 39273689, 2024). "It has been revealed that in lung, melanoma, and breast cancer patients, the circulating tumor cells expressing CD44 was a prognostic marker for brain metastases." (PMID 38783892, 2024). "According to existing literature, CD44 is highly expressed in stem cells from breast cancer, gastric cancer, and oral squamous cell carcinoma, while CD24 is typically expressed at lower levels." (PMID 39247186, 2024). "These N-GQDs were conjugated with hyaluronic acid (HA) to target CD44 overexpressed on MCF-7 breast cancer cells." (PMID 38730959, 2024). "When stimulated by prolactin, breast cancer cells increase CD44, a surface receptor mediating the endocytosis of hyaluronate-bound iron, resulting in the accumulation of iron in cancer cells." (PMID 39201626, 2024). "In CD44+ MDA-MB-231 breast cancer cells, JE22-NP displayed a cell viability half maximal efficacy concentration of 49 nM, significantly reducing cell viability." (PMID 38612911, 2024).